CIP2A (cellular inhibitor of PP2A)
Diseases named in the same sentence as CIP2A in open-access papers (continued):
Sharing a sentence is not in itself a finding about the gene and the disease.
hepatocellular carcinoma (34 papers, 2011 to 2025). A malignant tumor that arises from hepatocytes. "CIP2A overexpression is associated with poor patient outcomes in numerous solid tumors, including NB, hepatocellular carcinoma, and lung cancer." (PMID 39594793, 2024). "Intriguingly, recent reports have documented that lncRNA LINC00665 encodes a 52-amino acid (aa)-long short peptide CIP2A-BP in triple-negative breast cancer and hepatocellular carcinoma, where the short peptide is capable of participating in cancer pathogenesis." (PMID 37285335, 2023). "CIP2A gene polymorphisms and hepatocellular carcinoma susceptibility has been reported." (PMID 25015035, 2014). "Furthermore CIP2A gene polymorphisms and hepatocellular carcinoma susceptibility has been reported." (PMID 25015035, 2014). "Another study on cervical, endometrial, and liver carcinoma demonstrated that the oncogene CIP2A, is regulated by ELK1 and ETS1 and ultimately leads to augmented cell proliferation." (PMID 40862737, 2025). "CIP2A has been found to be overexpressed in the serum and cells of patients with different types of cancers, such as hepatocellular carcinoma (HCC), prostate carcinoma and breast carcinoma." (PMID 34144694, 2021). "Currently, it has been determined that CIP2A is overexpressed in the sera and cells of patients with different types of cancers, such as prostate, breast, and hepatocellular carcinoma (HCC)." (PMID 32321509, 2020). "So far CIP2A has been targeted in a limited number of cancers, such as hepatocellular carcinoma, as well as oral cancer." (PMID 27144172, 2016). "CIP2A has been found to be overexpressed in several human malignancies including hepatocellular carcinoma, gastric cancer, head and neck cancer, colon cancer, breast cancer, prostate cancer and NSCLC." (PMID 25537503, 2015). "Bortezomib sensitizes hepatocellular carcinoma cells to CS-1008, an anti-human death receptor 5 antibody, through the inhibition of CIP2A." (PMID 25015035, 2014). "CIP2A represents a major factor through which erlotinib derivatives induce apoptosis in hepatocellular carcinoma cells." (PMID 25015035, 2014). "CIP2A is highly expressed in hepatocellular carcinoma and its expression predicted poor prognosis in this cancer." (PMID 25015035, 2014). "Ectopic expression of CIP2A decreased AKT-related PP2A activity whereas silencing CIP2A increased this activity, indicating that CIP2A negatively regulates AKT-related PP2A activity in hepatocellular carcinoma cells." (PMID 25015035, 2014). "Bortezomib (a proteosome inhibitor used in clinics on myeloma patients) congeners induced apoptosis in hepatocellular carcinoma cells via CIP2A inhibition." (PMID 25015035, 2014). "PP2A dephosphorylates pAkt and CIP2A enhances PI3K/mTor signalling by inhibiting PP2A mediated dephosphorylation of pAKT in hepatocellular carcinomas (HCC)." (PMID 24098375, 2013). "In hepatocellular carcinoma cells, CIP2A up-regulates phospho-Akt (pAkt) and decreases Akt-related PP2A activity, whereas silencing CIP2A re-activates PP2A." (PMID 21655278, 2011). "CIP2A has been previously shown to be very long lived protein in hepatocellular carcinoma cell line." (PMID 21445343, 2011). "Recently, CIP2A was also shown to inhibit Akt kinase-associated PP2A activity and by these means to protect human hepatocellular carcinoma cells from bortezomib-induced apoptosis." (PMID 21445343, 2011). "Finally, the natural CIP2A inhibitors, ethoxysanguinarine and gambogenic acid, sensitized lung and hepatocellular cancer cells to chemotherapy." (PMID 31214504, 2019). "Inhibition of CIP2A determined erlotinib-induced apoptosis in hepatocellular carcinoma." (PMID 25015035, 2014). "In our previous studies, we demonstrated that bortezomib, a proteasome inhibitor, induced apoptosis via proteasome-independent inhibition of CIP2A in triple-negative breast cancer cells, hepatocellular carcinoma cells, leukemia cells and head and neck cancer cells." (PMID 25228280, 2014).
hepatocellular carcinoma (continued). "A recent report showed that CIP2A could protect the hepatocellular carcinoma (HCC) cell lines from bortezomib-induced apoptosis by inhibiting phosphor-AKT-associated PP2A phosphatase activity." (PMID 25109354, 2014). "CIP2A is highly expressed in hepatocellular carcinoma and its expression predicts poor prognosis." (PMID 25015035, 2014). "In hepatocellular carcinoma, CIP2A is found to mediate PP2A-dependent Akt inactivation." (PMID 21610708, 2011). "More importantly, CIP2A overexpression has been detected in a broad range of malignancies, including hepatocellular carcinoma (HCC) and bladder carcinoma, in which its expression correlates with disease progression." (PMID 41146310, 2025). "Here, we identify the long non-coding gene LINC00665 and its short peptides (CIP2A-BP) in hepatocellular carcinoma (HCC) and explore how they contribute to HCC progression." (PMID 35350239, 2022). "The inhibition of CIP2A has been shown to determine the effect of bortezomib on apoptosis and PP2A-dependent AKT inactivation in hepatocellular carcinoma indicating that CIP2A may be a biomarker for predicting clinical response of bortezomib in hepatocellular carcinoma treatment." (PMID 25015035, 2014). "Cancerous inhibitor of protein phosphatase 2A (CIP2A) is a human oncoprotein which is overexpressed in many cancers, including hepatocellular carcinoma (HCC), lung, colon, prostate, ovarian, cervical, breast, head and neck cancers and leukemia." (PMID 24335617, 2013). "Previously, we reported that cancerous inhibitor of protein phosphatase 2A (CIP2A) mediates the apoptotic effect of bortezomib in hepatocellular carcinoma (HCC)." (PMID 23383345, 2013). "CIP2A, an inhibitor of PP2A in cancer, was first identified as a 90 kDa protein in human hepatocellular carcinoma." (PMID 37097392, 2023). "Previously, it was also shown that CIP2A overexpression negatively regulates Akt-related PP2A activity and upregulates pAkt in hepatocellular carcinoma cells." (PMID 28938602, 2017). "In our previous studies, we demonstrated that bortezomib, a proteasome inhibitor, induced apoptosis via proteasome-independent inhibition of CIP2A in TNBC cells, hepatocellular carcinoma cells, leukemia cells and head and neck cancer cells." (PMID 26824320, 2016). "GEA, a natural compound derived from Garcinia hanburyi, targets CIP2A by inducing CIP2A degradation via the ubiquitin–proteasome pathway, disrupting oncogenic signaling pathways like MYC and phosphorylated Akt and enhances the sensitivity of hepatocellular carcinoma cells to anticancer agents." (PMID 41155727, 2025). "The proteasome inhibitor bortezomib down-regulated CIP2A in a dose- and time-dependent manner in all sensitive hepatocellular carcinoma (HCC) cell lines, whereas no alterations in CIP2A were found in resistant PLC5 cells." (PMID 37097392, 2023).
lung cancer (31 papers, 2011 to 2025). A malignant neoplasm involving the lung. "Since smoking is the main cause of lung cancer, we re‐analyzed the expression levels of CIP2A only in samples having smoking history." (PMID 41362702, 2025). "Our study demonstrates that high CIP2A expression is significantly associated with poorer overall survival in patients with lung cancer (log-rank p = 0.0051)." (PMID 40943297, 2025). "Our study demonstrates that high CIP2A expression is significantly associated with poorer overall survival in patients with lung cancer, as shown by Kaplan–Meier survival analysis." (PMID 40943297, 2025). "Recent studies have linked CIP2A expression to EMT in lung cancer, a process whereby epithelial cells lose their cell–cell adhesion properties and acquire a more migratory and invasive mesenchymal phenotype, which is crucial for tumor invasion and metastasis." (PMID 41155727, 2025). "Knockdown of RING1 increased lung cancer cell proliferation and migration in vitro and in vivo, linked to the upregulation of CIP2A and its downstream molecules, c‐MYC and Cyclin B1." (PMID 41362702, 2025). "To investigate the clinical significance of CIP2A expression in lung cancer, we first analyzed its association with various clinicopathological characteristics." (PMID 40943297, 2025). "Elevated CIP2A expression is associated with poor prognosis, chemoresistance, and increased metastatic potential in lung cancer patients." (PMID 41155727, 2025). "As high CIP2A levels are also implicated in disease progression in acute myeloid leukemia, breast, bladder, cervical, colon, hepatocellular and lung cancer, it will be of interest to ascertain if these tumors also exhibit an antiapoptotic phenotype." (PMID 26987906, 2016). "CIP2A-associated cell proliferation was performed by knock down or overexpression of CIP2A in lung cancer cells." (PMID 26560124, 2015). "CIP2A is a tumor-associated autoantigen in lung cancer, which promote lung cancer proliferation partially through MKK4/7-JNK signaling pathway." (PMID 26560124, 2015). "During the search of novel tumor-associated autoantigens in lung cancer patients, we found that CIP2A was overexpressed in lung cancer and elicited autoimmune response in lung cancer patients." (PMID 26560124, 2015). "The role of CIP2A in mediating interleukin-10 effect in the progression of human papillomavirus (HPV)-associated lung cancer has been recently studied." (PMID 25015035, 2014). "The multivariate logistic regression analysis clearly demonstrates that smoking is the only significant variable associated with CIP2A overexpression in lung cancer in our setting (p = 0.008)." (PMID 21655278, 2011). "Taken together, CIP2A is overexpressed in lung cancer tissues compared to normal lung tissues and the resultant overexpression can be considered as a diagnostic factor for clinical lung cancer detection." (PMID 26560124, 2015). "High CIP2A expression in lung cancer correlates with poor prognosis, increased tumor proliferation, and resistance to targeted therapies or chemotherapy." (PMID 41155727, 2025). "Collectively, our data support a model in which CIP2A promotes lung cancer progression via coordinated regulation of p-AKT, AMPK suppression, and tumor microenvironment remodeling." (PMID 40943297, 2025). "Collectively, these results demonstrated that high expression of CIP2A can promote cell growth and migration of lung cancer cells." (PMID 41362702, 2025). "In this analysis, CIP2A showed a significant difference in abundance between lung cancer tissues and adjacent normal tissues." (PMID 41362702, 2025). "In this study, CIP2A expression was found to be higher in lung cancer tissues compared to adjacent normal tissues." (PMID 41362702, 2025). "Collectively, higher CIP2A expression followed by RING1 reduction in lung cancer cells increases cell proliferation by c‐MYC and Cyclin B1 upregulation through inhibition of PP2A activity." (PMID 41362702, 2025).
lung cancer (continued). "To investigate the expression and significance of CIP2A protein in lung cancer, we evaluated CIP2A protein levels between lung cancer and adjacent normal tissues from patients." (PMID 41362702, 2025). "This Kaplan–Meier survival curve illustrates the overall survival probabilities of patients with lung cancer stratified by CIP2A expression levels, using a cutoff point of 218.33." (PMID 40943297, 2025). "In the following sections, we explore potential biological connections between these markers, CIP2A, and lung cancer pathogenesis." (PMID 40943297, 2025). "The development and progression of lung cancer involve the dysregulation of several molecular pathways, including those involving CIP2A, RING1, and DNMT1 proteins." (PMID 41362702, 2025). "It was also found that RING1 KD promotes lung cancer cell proliferation by upregulating CIP2A expression followed by increase of c‐MYC, and Cyclin B1." (PMID 41362702, 2025). "These agents are commonly used in lung cancer treatment, but CIP2A overexpression impairs their efficacy by enhancing the survival of signaling pathways and reducing apoptotic responses." (PMID 41155727, 2025). "Results in this study revealed that CIP2A expression is frequently upregulated in lung cancer tissues." (PMID 41362702, 2025). "CIP2A is a significant prognostic biomarker in lung cancer, contributing to tumor progression through modulation of angiogenesis and metabolic pathways." (PMID 40943297, 2025). "CIP2A is an oncogenic protein that plays a critical role in the development and progression of several types of cancer, including lung cancer." (PMID 41362702, 2025). "It was also found that CIP2A promotes lung cancer cell proliferation by inhibiting the activity of PP2A, a tumor suppressor that regulates multiple signaling pathways involved in cell growth and apoptosis." (PMID 41362702, 2025). "In this study, we showed that CIP2A functions as an oncogene in lung cancer that upregulated the c‐MYC and Cyclin B1." (PMID 41362702, 2025). "The expression of miRNA-383-5p is downregulated in lung cancer tissues and plays an antiproliferative role by targeting CIP2A." (PMID 37592783, 2023). "CIP2A has been found to be highly expressed in BC, nasopharyngeal carcinoma, cholangiocarcinoma, and non‐small cell lung cancer." (PMID 37706625, 2023). "In lung cancer cells, inhibition of CIP2A led to reduced protein levels of c-Myc, enhanced apoptosis, and decreased cell proliferation." (PMID 36313570, 2022). "Cell proliferation regulating inhibitor of phosphatase 2A (CIP2A) has been shown to activate Akt signaling via inhibition of Akt dephosphorylation in different types of cancer, including lung cancer." (PMID 33804833, 2021). "Taken together, these data further support a role of CIP2A in the response of lung cancer cells to EGFR tyrosine kinase inhibitors." (PMID 33804833, 2021). "Collectively, these results suggest that EA induced autophagy to inhibit lung cancer cell proliferation by down‐regulating CIP2A." (PMID 30353639, 2019). "We found that CIP2A in lung cancer cells was dramatically decreased upon EA treatment in a dose‐dependent manner." (PMID 30353639, 2019). "EA was capable of inhibiting lung cancer cell proliferation and inducing autophagy, which was regulated by CIP2A oncoprotein." (PMID 30353639, 2019). "EA elevated autophagy‐associated cell death by down‐regulating the expression of cancerous inhibitor of protein phosphatase 2A (CIP2A), and CIP2A overexpression attenuated EA‐induced autophagy of lung cancer cells." (PMID 30353639, 2019). "Previous studies have shown that high CIP2A expression was highly correlated with cancer invasiveness and poor prognosis in lung cancer; thus CIP2A is used as a potential molecular marker and therapeutic target for the treatment of lung cancer." (PMID 30759826, 2019).
lung cancer (continued). "In accordance with this finding, EA dramatically suppressed tumour growth in a nude mouse model of lung cancer by activating autophagy and down‐regulating CIP2A levels." (PMID 30353639, 2019). "Increased expression levels of CIP2A have been reported in gastric, colon, breast, and lung cancers." (PMID 30380781, 2018). "When stratified by cancer type, increased CIP2A expression had an unfavorable impact on the OS of patients with lung cancer (pooled HR = 1.842, 95% CI 1.286–2.638, P = 0.001) and colorectal cancer (pooled HR = 1.897, 95% CI 1.108–3.249, P = 0.020)." (PMID 30044786, 2018). "An increased expression of CIP2A had been detected in multiple malignancies, such as gastric cancer, breast cancer, prostate cancer, lung cancer, papillary thyroid carcinoma and head and neck squamous cell carcinomas." (PMID 30044786, 2018). "Overexpression of CIP2A in lung cancer not only triggers immune response in lung cancer patients but also promotes lung cancer cell proliferation." (PMID 26560124, 2015). "Therefor, loss-of-function and gain-of-function studies suggested that CIP2A promote cell proliferation of lung cancer cells." (PMID 26560124, 2015). "This is in contrast to previous studies in ovarian, tongue and non–small cell lung cancers where cytoplasmic CIP2A is reported to be an independent marker of reduced OS 9,14,31." (PMID 25663244, 2015). "The higher percentage of anti-CIP2A positive lung cancer patients than that in normal human suggested CIP2A was more antigenic in lung cancer than in normal human." (PMID 26560124, 2015). "The presence of autoantibody against CIP2A in sera from lung cancer patients also suggested that CIP2A was activated at early stage of lung cancer initiation." (PMID 26560124, 2015). "Commercially available tumor tissue array was used to examine the expression level of CIP2A in lung cancer tissue specimen." (PMID 26560124, 2015). "To validate our finding that CIP2A regulates JNK phosphorylation in lung cancer cells, we treated the cells with EGF to activate the growth factor-induced JNK activation for 15 mins." (PMID 26560124, 2015). "A set of 72 samples of lung cancer tissues, and 63 samples of normal lung tissues were analyzed with immunohistochemistry (IHC) by using monoclonal CIP2A antibody." (PMID 26560124, 2015). "In this study, we not only found that autoantibodies against CIP2A had very high frequency (25.7 vs 4.9 % in normal) in the sera from lung cancer patients but also the overexpression of CIP2A in more than 60 % lung cancer tissues." (PMID 26560124, 2015). "During our evaluation of CIP2A expression in different lung cancer cell lines, one interesting observation is the expression of CIP2A in immortalized cell line BEAS-2B but not in another immortalized cell line HBEC3." (PMID 26560124, 2015). "In contrast to the immortalized cell lines, all of these six lung cancer cell lines are expressing endogenous CIP2A with distinct expression level." (PMID 26560124, 2015). "In this study, we mainly demonstrated that CIP2A is overexpressed in lung cancer and mount immune response in a high percentage of lung cancer patients." (PMID 26560124, 2015). "H1299 and H146 were expressing higher level of CIP2A than other lung cancer cells while H460 and H69 were expressing lower level of CIP2A." (PMID 26560124, 2015). "To gain a better view of the immune response triggered by CIP2A in lung cancer patients, we used ELISA to measure the frequency of autoantibodies against CIP2A in additional 105 sera from lung cancer patients." (PMID 26560124, 2015). "To establish the role of CIP2A in the cell proliferation of lung cancer cells, we first examined the expression of CIP2A in four different lung cancer cell lines, A549, NCI-H838 (H838), NCI-H1299 (H1299) and NCI-H460 (H460)." (PMID 25109354, 2014).